EML4 (EMAP like 4)
Diseases named in the same sentence as EML4 in open-access papers (continued):
Sharing a sentence is not in itself a finding about the gene and the disease.
lung cancer (continued). "ALK fusion proteins are HSP90 clients, and it has already been shown in preclinical and clinical studies that HSP90 inhibition is highly effective against EML4-ALK-positive lung cancer as well as against ALK-positive ALCL cells in vitro." (PMID 24509625, 2014). "In lung cancers, ALK mutations appear to develop during clinical treatment with crizotinib and their generation probably renders EML4-ALK resistant not only to crizotinib but also to other ALK inhibitors." (PMID 25083769, 2014). "The EGFR/KRAS mutations and the EML4-ALK translocation are called driver mutations because they are responsible for both the initiation and maintenance of lung cancer." (PMID 23341890, 2013). "Although rarer than lung cancer with EGFR mutation, the identification of kinase gene fusions, including EML4-ALK, in lung cancer leads to molecularly-targeted therapy with kinase inhibitors." (PMID 23617234, 2013). "More recently, HGF was reported to induce resistance to ALK selective inhibitors in EML4-ALK lung cancer and BRAF inhibitors in BRAF mutant melanoma." (PMID 23690929, 2013). "In this article, we review the four commonly known oncogenic driver mutations in lung cancer – EGFR mutations at exons 18 – 21, KRAS gene mutation at codons 12 and 13, EML4-ALK fusion genes and deregulation of MET signaling." (PMID 27234388, 2013). "Several groups reported that mucinous cribriform pattern and signet ring cell are characteristic histological features of EML4-ALK positive human lung cancer." (PMID 23418494, 2013). "The characteristics of EML4-ALK in lung cancers remain to be elucidated, particularly in Chinese patients with NSCLC." (PMID 23341890, 2013). "In lung cancer, the fusion of ALK and echinoderm microtubule-associated protein-like 4 (EML4) leads to constitutive activation of the kinase." (PMID 24376513, 2013). "Recently, the EML4/ALK fusion protein has also been demonstrated to trend toward positive prognostication in lung cancer." (PMID 23844053, 2013). "In this report, we described a case of synchronous bilateral lung cancers with EML4-ALK positive adenocarcinoma in the right lung and adenocarcinoma in situ in the left, which was EML4-ALK negative." (PMID 23617234, 2013). "In the present study, the detection rate of EML4-ALK fusion gene increased from 1.0% (2/202 patients with unselected lung cancer) in the test set to 5.1% (8/158 patients with EGFR and KRAS mutation-negative adenocarcinoma) in the validation set." (PMID 23936355, 2013). "ALK inhibitors are now being developed as drugs; the TKI crizotinib is in use in lung cancer patients carrying the EML4-ALK fusion protein." (PMID 24376513, 2013). "Early-phase clinical trials have revealed that TKIs that target ALK show marked efficacy in patients with lung cancer positive for EML4–ALK." (PMID 22240786, 2012). "Further experience and the understanding of the lung cancer molecular biology are required for the better treatment of the cases with both EGFR mutation and EML4-ALK fusion gene." (PMID 23181703, 2012). "Depletion of BIM and overexpression of Survivin each inhibited TAE684-induced apoptosis, suggesting that both upregulation of BIM and downregulation of Survivin contribute to TAE684-induced apoptosis in EML4-ALK-positive lung cancer cells." (PMID 22928112, 2012). "Collectively, these data suggested that simultaneous interruption of STAT3-survivin and ERK–BIM signalling pathways is required for the induction of apoptosis in EML4–ALK-positive lung cancer cells." (PMID 22240786, 2012). "In conclusion, our results suggest that interruption of both STAT3-survivin and ERK–BIM signalling is required for the induction of apoptosis in lung cancer cells harbouring EML4–ALK." (PMID 22240786, 2012). "Recently, small molecules have been developed to treat lung cancer in patients carrying such mutated genes as EGFR and EML4-ALK fusion genes." (PMID 21079797, 2010).
lung cancer (continued). "This gene which is known to play a role in lymphomas has been recently shown to be activated in lung cancer either by gene fusion with EML4 or amplification." (PMID 19594952, 2009). "We evaluated the expression of the EML4–ALK transcript in 104 lung cancer cases and in 645 gastrointestinal and breast cancer samples." (PMID 18414414, 2008). "Among other commonly detected mutations in lung cancer patients, KRAS mutations were identified in approximately 4.5 % of cases, while EML4-ALK fusions were detected in only 0.5 % of patients, suggesting potential limitations of ctDNA profiling in detecting fusions." (PMID 40503459, 2025). "Next, we also tested WE-CL13-GP181M-185W-492I in a lung cancer model of Eml4-Alk translocation." (PMID 41086811, 2025). "There are various fusion breakpoints in multiple exons of EML4 in EML4-ALK-positive lung cancer." (PMID 38829559, 2024). "In this study, we established tumoroids (PDT-LUAD#119) from a patient with lung cancer harboring EML4-ALK that could be cultured for 12 months." (PMID 38829559, 2024). "To define the role of the tumor microenvironment (TME) in mediating response to TKI therapy in ALK positive lung cancer, we have used an orthotopic immunocompetent model whereby murine EML4-ALK fusion-positive lung cancer cells are directly implanted into the lungs of syngeneic C57BL/6 mice." (PMID 36739466, 2023). "Moreover, in all the H3122 lung cancer cell line samples bearing the EML4::ALK fusion, CircFusion detected f-circA22-E4 (5–17 reads per sample, average dataset depth of 15 M read pairs)." (PMID 36585787, 2023). "We next evaluated the antitumor activity of XMU‐MP‐5 in EML4‐ALK‐positive H3122 lung cancer cells." (PMID 34845836, 2022). "One patient with lung cancer and EML4-ALK fusion treated with alectinib had a complete response." (PMID 35323355, 2022). "In line with studies on ALK-positive lung cancers, which have showed the variable clinical outcome of patients with different EML4-ALK fusion variants, we also observed prolonged PFS outcome in patients harboring the v1 variant compared with those carrying the v3 variant." (PMID 36369474, 2022). "The pathogenesis of lung cancer induced by EML4-ALK has been confirmed by evidence, and the rapid development of lung cancer is mainly caused by overexpression of EML4-ALK in type II alveolar epithelial cells through the Clara cell secretory protein (CCSP) or surfactant protein c (SPC) promoter." (PMID 36591504, 2022). "Crizotinib is a commonly used drug to treat EML4-ALK-positive lung cancer patients." (PMID 34633654, 2022). "Heat shock protein 90 (Hsp90) has been implicated in the assembly of multiple chaperone complexes, regulating the stability and function of client proteins such as wild type c-RAF, mutant BRAF, mutant EGFR, as well as the EML4-ALK fusion protein in lung cancer." (PMID 35326726, 2022). "Here, we present the case of choroidal metastases secondary to lung cancer and EML4-ALK translocation in a 57-year-old woman who firstly underwent resection of lung lesions followed by oral administration of crizotinib without local treatment or systemic chemotherapy." (PMID 35433411, 2022). "Based on our results, we conclude that EML4-ALK may be useful for predicting potential responses to ALK inhibitors used as therapeutic options for patients with lung cancer." (PMID 36185247, 2022). "Of note, non‐small cell lung cancer is often associated with an improved prognosis in patients with positive driver gene mutations, such as epidermal growth factor receptor (EGFR) mutation and EML4‐ALK gene mutation." (PMID 35523730, 2022). "Several experiments supported a pivotal role for EML4–ALK in lung cancer." (PMID 36185247, 2022). "The EML4‐ALK “fusion‐type” oncogene is critical in driving oncogenesis in a subset of lung cancers." (PMID 34668636, 2022).
lung cancer (continued). "This kind of alteration could also be a potential biomarker for targeted therapy, such as crizotinib for treating lung cancer with EML4-ALK translocation." (PMID 35163506, 2022). "Substantial breakthrough discoveries, including the identification of lung cancer–specific oncogenic drivers (e.g., EGFR mutations, EML4-ALK fusion genes) and the development of molecular inhibitors of these pathogenic factors, have improved outcomes for patients with advanced-stage lung cancer." (PMID 35166243, 2022). "We hypothesized that the JAK2-STAT pathway plays an important role in developing lung cancer driven by EML4-ALK." (PMID 34090412, 2021). "Mouse NIH3T3 cells expressing human EML4-ALK fusion formed foci in culture and subcutaneous tumors in nude mice, indicating that EML4-ALK might be a key factor for the development of lung cancer." (PMID 34090412, 2021). "While in the young lung cancer group, the incidence of EML4-ALK was 11.0%, which was much higher." (PMID 35096611, 2021). "Interestingly, the ALK inhibitor Ceritinib decreased mTOR activity and increased GFP-WIPI1 dot formation in H3122 and H2228 EML4-ALK+ lung cancer cells, suggesting autophagy activation." (PMID 33907223, 2021). "All are well studied and used in the treatment of EML4-ALK(+) lung cancer." (PMID 33466277, 2021). "Similarly, a CRISPR/cas9 lentiviral vector was used to generate EML4-ALK positive lung cancers in mice models via intratracheal or intrapulmonary inoculation." (PMID 33806977, 2021). "Our findings may provide a new approach for treating the EML4–ALK-positive lung cancer that aims to disrupt protein condensates." (PMID 33976114, 2021). "Combined TAE684 (ALK tyrosine kinase inhibitors) with PI3K inhibitor synergistically inhibited the proliferation of EML4-ALK-positive lung cancer cells and inhibition of PI3K/AKT signaling may conquer resistance to ALK-targeted treatment." (PMID 34234236, 2021). "Because EML4-ALK interacted with the JAK2-STAT pathway resulting in the phosphorylation of STAT proteins in EML4-ALK-positive lung cancer cells, we investigated whether IL4 or IL6 activated the JAK2-STAT pathway in these cells." (PMID 34090412, 2021). "P-JAK2 and p-STAT6 appeared in the cytoplasm of lung cancer cells positive for EML4-ALK." (PMID 34090412, 2021). "Furthermore, reversing ALK-TKI and inhibiting angiogenesis in combination with alectinib and apatinib, thus inhibits ALK and VEGF R2 controlling the progression of the EML4-ALK fusion gene lung cancers." (PMID 34660278, 2021). "ALK and p-ALK status were investigated in the nine established MCC cell lines and in the lung carcinoma cell line NCI-H2228, which harbors a fusion gene formed from genes Echinoderm microtubule-associated protein-like 4 (EML4) and ALK, and was used as a positive control." (PMID 34029351, 2021). "Subsequently, we targeted the EML4-ALK v1 transcript in H3122 lung cancer cells." (PMID 33255340, 2020). "EML4-ALK is an oncogenic fusion protein involved in the pathogenesis of lung cancer." (PMID 32344689, 2020). "Summing up this interesting data, synergistic effects of combined TAE684 and radiotherapy in EML4‐ALK positive lung cancer cells are demonstrated: Not only does ALK‐inhibition enhance the effect of canonical photon radiotherapy, but also of particle irradiation using carbon ions." (PMID 31799812, 2020). "These clinical observations could echo with prior studies which showed that EML4-ALK oncoprotein can upregulate the PD-L1 expression in lung cancer cells." (PMID 33273548, 2020). "Similarly, in a recent study, EML4-ALK variant 3(V3) was proposed to mediate microtubule stabilization through NEK7 and NEK9, accelerating cell migration in EML4-ALK lung cancer." (PMID 33364979, 2020). "A G1128A mutation in EML4-ALK lung cancers does not appear to affect the drug’s affinity for the enzyme but rather induces a conformational change that increases the kinase activity." (PMID 32283832, 2020).
lung cancer (continued). "This study investigated the previously unknown mechanism of responsiveness and resistance to PEM in EML4-ALK-rearranged lung cancer." (PMID 31795298, 2019). "Anaplastic lymphoma kinase (ALK) is a receptor tyrosine kinase that has been recognized as a therapeutic target for EML4-ALK fusion-positive nonsmall cell lung cancer (NSCLC) treatment using type I kinase inhibitors such as crizotinib to take over the ATP binding site." (PMID 31388026, 2019). "As the most common sensitive gene mutations for lung cancer, a fusion gene between the anaplastic lymphoma kinase (ALK) gene and echinoderm microtubule associated protein-like 4 (EML4) was identified in 3% to 7% of unselected NSCLC patients, and further proved to be a potent oncogenic driver." (PMID 30658713, 2019). "Mutant EGFR, Kras, and EML4-ALK are critical driver oncogenes in lung cancers." (PMID 30971692, 2019). "Patients with lung cancer that carry EML4-ALK fusion respond to tyrosine kinase inhibitors (TKI), such as crizotinib, and therefore unambiguous detection of ALK status in a lung cancer specimen is critical for a treatment decision and predicts the outcome of the affected patient." (PMID 31412611, 2019). "In our own studies, expression array and RNAseq experiments reveal broad and marked induction of IFN-stimulated genes including CXCL10 in HNSCC cell lines and EGFR mutant lung cancer cell lines treated with EGFR inhibitors as well as EML4-ALK-driven cell lines treated with crizotinib." (PMID 29458371, 2018). "Importantly, these models also displayed sensitivity to ALK inhibition and thus serve as valuable tools to explore the mechanisms of EML4-ALK induced lung cancer and response to ALK targeted therapies." (PMID 29455675, 2018). "We further demonstrated that the second‐generation ALK‐TKI alectinib was much more effective than the first‐generation ALK‐TKI crizotinib in the in vivo imaging model, thus indicating the usefulness of alectinib against brain metastases induced by EML4‐ALK lung cancer." (PMID 29125233, 2017). "The EML4-ALK fusion was once thought to occur only in lung cancer." (PMID 28535796, 2017). "The EWSR1/FLI1 and EML4/ALK1 translocation common in solid tumors such as Ewing Sarcoma and lung cancer, could also generate associated f-circRNAs." (PMID 28279183, 2017). "However, EML4-ALK-positive lung cancer is often highly progressive, and careful follow-up is therefore essential in these patients." (PMID 26964537, 2016). "Few reports have focused on the imaging findings of EML4-ALK-positive lung cancer." (PMID 26964537, 2016). "Many lung cancer driver gene mutations have been identified, such as EGFR, KRAS, ROS, EML4-ALK." (PMID 27223066, 2016). "Interestingly, cross-validation using the lung cancer-derived EML4-ALK fusion showed both similarities and key differences in the effect of mutations on particular drugs." (PMID 27009859, 2016). "Therefore, it is necessary to consider the detailed imaging features of EML4-ALK-positive lung cancer." (PMID 26964537, 2016). "EML4-ALK-positive lung cancer presenting with GGN is relatively rare." (PMID 26964537, 2016). "Therefore, follow up studies should include combining imetelstat with targeted therapies such as erlotinib in EGFR mutant lung cancer and crizotinib in EML4-ALK fusion lung cancer." (PMID 27192120, 2016). "The JAK-STAT signaling pathway, an important downstream signaling pathway of EML4-ALK, is aberrantly sustained and activated in EML4-ALK-positive lung cancer cells fusion gene, but the underlying reason remains unknown." (PMID 27666544, 2016).
lung cancer (continued). "Further consideration of the growth speed of EML4-ALK-positive lung cancer is needed; for example, the tumor doubling time may be measured." (PMID 26964537, 2016). "In addition, we discuss potential future treatment strategies in ALK-TKI-naïve and -resistant patients with lung cancer harboring the EML4-ALK fusion gene." (PMID 25941796, 2015). "The success of EGFR and ALK inhibitor therapies in lung cancer patients with EGFR mutations and EML4-ALK translocations initiated the era of targeted therapy in advanced NSCLC and shifted treatment from platinum-based chemotherapy to molecularly targeted therapy." (PMID 25789627, 2015). "Chemotherapy is currently the standard of care for ADC lung cancer patients in the absence of EGFR or other targetable molecular alterations (EML4-ALK), with erlotinib approved only for EGFR-mutated ADC patients in first-line treatment." (PMID 26247735, 2015). "The recent advances in genomics have proved to be linked to prognosis and response to therapy, for instance BRAF inhibitors have changed the landscape of BRAF V600 E mutant melanomas, and ALK inhibitors have dramatically changed the outcome of EML4-ALK mutant lung cancer patients." (PMID 25859559, 2015). "Furthermore, few studies have described the imaging findings related to EML4-ALK gene fusions in lung cancer." (PMID 26332764, 2015). "Furthermore, we have also examined the phosphorylation status after crizotinib treatment in H2228 cells, a confirmed EML4-ALK positive lung cancer cell line, and discovered the phosphorylation level of STAT3 was downregulated as well." (PMID 26384345, 2015). "EML4-ALK-positive lung cancers are highly sensitive to ALK inhibition." (PMID 24842630, 2014). "H2228 cells express EML4 moderately but at higher levels than other lung cancer cell lines." (PMID 24842630, 2014). "We performed RT-PCR and assayed the EML4 DNA levels of certain lung cancer cell lines." (PMID 24842630, 2014). "Comparison of RT-PCR, IHC and FISH for detection of EML4-ALK positive lung cancers." (PMID 23922677, 2013). "EGFR gene mutations, KRAS gene mutations, EML4-ALK rearrangements and altered MET signaling are widely recognized alterations that play important roles in both the biological mechanisms and the clinical sensitivity to treatment in lung cancer." (PMID 27234388, 2013). "Therefore, it is necessary to understand the correlations between EML4-ALK and EGFR/KRAS mutations in lung cancer patients." (PMID 23341890, 2013). "The most frequent ALK fusion in lung cancer is EML4-ALK (4–7%), and the second is KIF5B-ALK (0.5%)." (PMID 22347464, 2012). "We report a rare case of lung cancer harboring both EGFR mutation and EML4-ALK fusion gene." (PMID 23181703, 2012). "Therefore, this study was undertaken to evaluate the presence of the EML4–ALK transcript in 749 cases of lung cancer and 2 major solid carcinomas (gastrointestinal and breast cancers)." (PMID 18414414, 2008). "The clinical features of lung cancers carrying mutations in the echinoderm microtubule associated protein-like (EML4)-ALK fusion gene include mild or never smoking, younger age, adenocarcinoma with an alveolar pattern or impression ring adenocarcinoma, and lack of EGFR or KRAS mutations." (PMID 40136367, 2025). "As one of the most important pathological types of lung cancer, in recent years, individualized lung adenocarcinoma treatments, including EGFR TKIs and EML4‐ALK, have been highly effective for the treatment of patients with EGFR mutations or harboring EML4‐ALK fusions." (PMID 34854250, 2022). "However, the molecular mechanisms involved in regulating cell proliferation and survival of lung cancer cells by EML4-ALK are still unknown." (PMID 34090412, 2021). "Approximately 80–85% of lung cancers count among non-small cell histology (NSCLC), and approximately 2–7% of NSCLC cases feature positivity for anaplastic lymphoma kinase (ALK) gene rearrangement or connection with echinoderm microtubule-associated protein-like 4 (EML4)." (PMID 33572278, 2021).